KRAS (KRas proto-oncogene, GTPase)
Diseases named in the same sentence as KRAS in open-access papers (continued):
Sharing a sentence is not in itself a finding about the gene and the disease.
cancer (continued). "To further investigate this hypothesis, we used SMARTpool siGENOME small interfering RNAs (siRNAs) to deplete KRas and GSK3α/β from a panel of eight mutant KRas-harboring human cancer cell lines and then determined the effects of silencing these genes on apoptosis and viability." (PMID 30514931, 2018). "Based on these results and our previous identification of the importance of KRAS mutations and NF-κΒ signaling in MPE development, we hypothesized that IKKα is required for sustained NF-κΒ activation and MPE induction by pleural-homed KRASMUT cancer cells." (PMID 29445180, 2018). "Several oncogenes such as Myc and KRas have been shown to alter glutamine metabolism leading to glutamine dependence, although the outcome can be strongly tissue and context dependent and some cancer cells produce glutamine from glutamate through a reaction depending on glutamine synthetase (GS)." (PMID 30122553, 2018). "It remains to be seen whether the SHP2 inhibitor can cooperate with other inhibitors to reduce the adaptive feedback that occurs through RTK signaling in response to inhibition of several major pathway nodes, such as with MAPK inhibition in KRAS mutant cancers." (PMID 28431544, 2017). "KRAS is the dominant oncogene in this cancer type and molecular rationale would indicate, that inhibitors of the downstream target MEK could be appropriate targeted agents, but clinical trials have failed so far to achieve statistically significant benefit in unselected patients." (PMID 28957417, 2017). "Interestingly, cancer cells with PTEN mutations but without KRAS alterations demonstrated a higher sensitivity to NVP-BEZ235 than those with KRAS alterations." (PMID 28008141, 2017). "Recently, a new mice model has been developed, called iKRAS, where pancreatic KRAS is placed under a tetracycline inducible promoter, providing a reliable and accurate model to trace the effects of KRAS contribution at different time points throughout cancer evolution." (PMID 28895920, 2017). "However, the prognostic value of KRAS mutation detected by cfDNA on survival in other cancer patients is still not completely clear." (PMID 28796802, 2017). "Therefore, we hypothesized that the combination of a key oncogene (KRAS) and additional pathway perturbation might be highly effective in killing cancer cells." (PMID 26716649, 2016). "Functional genetic screens have recently revealed that cancer cell lines expressing oncogenic KRAS are sensitive to interference with mitosis, but neither the mechanism nor the uniformity of anti-mitotic drug sensitivity connected with mutant KRAS expression are yet clear." (PMID 27412232, 2016). "Though KRAS codon 61 appeared as prognostic biomarker in stage III cancer, the rare event may indicate indeterminacy at present, considering the low codon 61 mutation frequency in CRC22, 27, confirmation of the prognostic value required further investigation with a larger sample size." (PMID 27074743, 2016). "Our result highlighted that the gross metabolic changes observed in G12C KRAS mutant cells growing in culture were also maintained in the derived xenograft model, suggesting that a simple in vitro cell model can give important insights into the metabolic alterations induced by cancer." (PMID 27329432, 2016). "Importantly, our screening strategy also identified previously undescribed drug interaction patterns and several novel combinations with high efficacy against KRAS-mutant cancers, for example, the combined inhibition of PLK1 and ROCK (CI=0.33 at median effective dose)." (PMID 27193833, 2016).
cancer (continued). "Also, this map may facilitate a better understanding of the biology of cancers driven by KRas mutants and may serve as the resource for prospective studies and development of antibody-free, high-throughput MS-based quantitation assays for cell-surface targets." (PMID 27894102, 2016). "Here we show a KRAS/CDK1 synthetic lethality that can be elicited with small molecule CDK1 inhibitors might also be added to the list of potential utilities for small molecule CDK inhibitors in cancer." (PMID 26881434, 2016). "Although an explanation for the sensitivity of Ras mutant lines to the combination remains to be determined, ongoing studies are evaluating the hypothesis that HDIs impair the glutamine utilization pathway, which has been shown to be important for KRAS-mutant cancers." (PMID 27634878, 2016). "Finally, we demonstrate here for the first time that KRAS-mutant cancer cell lines expressing elevated levels of MYC show increased sensitivity to several microtubule-interfering agents, opening up new avenues for therapeutic intervention and suggesting new strategies for patient stratification." (PMID 27412232, 2016). "No effective targeted therapies exist for cancers with somatic KRAS mutations." (PMID 27193833, 2016). "In conclusion, these findings may have important implications in NSCLC through the development of combination strategies (e.g. nutrient modification) to increase the killing of cancer cells expressing mutant KRAS, enhancing the selectivity and finally improving the therapeutic index." (PMID 27283493, 2016). "Hence, these surface molecules may serve as the first line of prospective targets to be further investigated using cancer cell lines expressing oncogenic KRas mutants or validated in human KRas-driven cancers using tissue protein arrays." (PMID 27894102, 2016). "Thus, the effect that oncogenic KRAS imposes on drug response appears independent of cellular status and the presence of additional cancer mutations." (PMID 27845624, 2016). "Therefore, the modulation of KRAS by miR-200c may explain why the downregulation of miR-200c during breast carcinogenesis can promote cancer progression." (PMID 26392416, 2015). "In addition, the overall lower degree of mutation load with respect to the methylation rate detected in CRC tissues (26.9% vs 57,2% in early stage cancers) might have contributed to enhance the dilution effect of wild type-KRAS DNA in the circulation." (PMID 25946211, 2015). "The preclinical experiments demonstrated trametinib had broad anticancer activity in multiple cancer models by inducing cell cycle arrest, apoptosis and growth inhibition in vitro and in vivo, especially in cancer cells with activating mutations of BRAF and KRAS in the MAPK pathway." (PMID 25915534, 2015). "This spectrum of changes might be one of the reasons why mutated KRAS has so far not been an helpful marker to further classify patients in different cancer subgroups." (PMID 26353932, 2015). "Classification of tumors solely by the presence of a mutation in KRAS, without defining the specific mutation, might not be enough to identify patients with a different response to therapy in cancers harboring a KRAS mutation." (PMID 26353932, 2015).
cancer (continued). "The antagonism between KRAS and the pro-acinar transcription factor network captures, at a genetic level, the tension between differentiation and malignant transformation that has long been hypothesized to exist in cancer." (PMID 26151762, 2015). "In CP, KRAS may be upregulated when its inhibitor (miR-193b) is downregulated, and the higher KRAS activity could induce a series of inflammatory programs that lead to cancer." (PMID 25905463, 2015). "Thus, compounds 1a-d and 2a-d were designed, synthesized and evaluated for selective G4 thermal stabilization comparing to duplex DNA, together with inhibition of cancer cell proliferation, induction of apoptosis and down-regulation of KRAS and HSP90 transcription and protein expression." (PMID 26024321, 2015). "Taken together, the observation of let-7d-5p/3p and multiple-miRNA targeting of IGF1R and KRAS is consistent with the safe-proof mechanism of miRNA regulation of crucial factors in cancer-related pathways to warranty continued advantages in the promotion and maintenance of the cancer phenotype." (PMID 25287248, 2014). "In summary, the possibility that in KRAS and BRAF mutant cancer cells differential signalling mechanisms that involve MEK supported the mutual exclusivity of these two mutations, lead to the target-specific cancer therapeutics in the form of monoclonal antibodies against EGF and VEGF receptors." (PMID 25361007, 2014). "Thus these events describe a single pathway, wherein the predominant event occurring in PDA is loss of p16ink4a, and suggest that restoring its biological function could represent a key means to limit the growth of KRAS driven cancers." (PMID 25156567, 2014). "Furthermore, they provide evidence that Smad3/TGFβ is controlled by KRAS in both cancers." (PMID 24878567, 2014). "Of interest, compared to KRAS-wild-type, overall, KRAS-mutated cancers more frequently exhibited cecal location (24% vs. 12% in KRAS-wild-type; P < 0.0001), CIMP-low (49% vs. 32% in KRAS-wild-type; P < 0.0001), and PIK3CA mutations (24% vs. 11% in KRAS-wild-type; P < 0.0001)." (PMID 24885062, 2014). "KRAS amplification is currently not used as a diagnostic or clinical management marker, but its utilization may be warranted in specific cancer types." (PMID 24874471, 2014). "As KRAS and BRAF mutations are associated with poor response to anti-EGFR therapy in some cancers, it has been suggested that screening for KRAS and BRAF mutations in RCC may be a promising strategy to identify patients who might respond to EGFR-targeted therapy." (PMID 28326248, 2014). "Thus, KRAS and EGFR might have a role as markers of lung function impairment that may reflect cancer risk." (PMID 23384026, 2013). "Because our aim was to compare the outcomes of KRAS codon 12 and 13 mutant cases with those characterized by other mutations, clinical data and FFPE specimens of the patients treated with cetuximab-containing regimens at seven Japanese cancer centers from July 2008 to April 2010 were collected." (PMID 24006859, 2013). "In this study we also observed that PIK3CA codon 545 substitutions account for 9.8% of PIK3CA mutations in CRC and, since the carcinoma carrying the PIK3CA p.Glu545Asp mutation did not present mutations in either KRAS or BRAF, it is conceivable that this mutation confers some selective advantage." (PMID 23548132, 2013). "Our and others' results suggest that the presence of a KRAS mutation (or other unknown alterations in these cells) could render H358 cells dependent on EGFR signaling and that EGFR would be a candidate therapeutic target in such cancers." (PMID 22436374, 2012).
cancer (continued). "In addition, activating mutations in BRAF, a member of the RAF gene family, which encode kinases that are regulated by members of the RAS protein family (HRAS, KRAS, and NRAS) and mediate cellular responses to growth signals, were found to be associated with microsatellite instability (MSI) cancers." (PMID 22931052, 2012). "Therefore, KRAS and BRAF mutations are promising targets for cancer detection and screening." (PMID 23208557, 2012). "In contrast to KRAS mutations, those in BRAF have the ability to cause genomic rearrangements in colon cells that can potentially sensitize them to apoptosis a major advantage in cancer therapeutics, since deregulation of apoptosis can lead to growth advantage in cancer cells." (PMID 21738740, 2011). "Considering recent evidence suggesting that PTEN mutation results in resistance to EGFR-targeted therapies, the inhibition of TOPK in KRAS and BRAF wild-type patients could represent an approach to improve clinical outcome in patients with either PTEN wild-type or mutated cancers." (PMID 19935791, 2010). "Besides these mutations we have also identified several mutated cancer drug targets or genes that are associated with treatment outcome, including BRAF, KRAS, FGFR2 and MTOR, which might help to choose optimal drug combinations." (PMID 21203531, 2010). "Thus, amplified wild-type KRAS might provide a growth advantage to cancer cells, not only by upregulating the basal cell growth, but also by conferring adaptability to changes in the environment, such as availability of growth factors and nutrients." (PMID 19545448, 2009). "For the other genes that presently resulted co-regulated by the two mutated KRAS isoforms with respect to the WT isoform, we could not find in the literature a correlation with cancer." (PMID 19087308, 2008). "Given the synergistic effects of FGF19 with MYC and KRAS, a therapeutic strategy targeting FGF19, MYC, and KRAS jointly is expected to become a new direction in cancer treatment." (PMID 41328353, 2026). "Building on the success of HPV and HBV vaccines, researchers are now developing innovative vaccine approaches targeting oncogenic drivers like KRAS, EGFR, and other early oncogenic neoantigens to intercept cancer before it emerges." (PMID 42001483, 2026). "Inhibition of IGF1R in this context reduces residual disease burden and cancer recurrence, underscoring the broader relevance of IGF1 signaling in KRAS driven cancer." (PMID 41526435, 2026). "Cancer cell viability was measured by Resazurin cytotoxicity assay and the gene and protein expression of APC, KRAS, TTN, HIF-1α, HIF-1β, and GLUT-1 were measured using rtPCR and ELISA." (PMID 41797969, 2026). "Additionally, we examined KRAS E4 alternative splicing patterns across various cancer cell lines and found that nearly all of them predominantly express the KRAS4B splicing variant, in contrast to the broader distribution of E4 inclusion rates observed in the TCGA cancer tissue database analysis." (PMID 41368203, 2026). "Elucidating these mechanisms is vital for designing targeted therapies against cancers driven by MYC and KRAS." (PMID 41328353, 2026). "Ongoing trials are evaluating targeted therapies (e.g., KRAS, PARP, and mTOR inhibitors), immunotherapies (e.g., checkpoint inhibitors, CAR-T cells, and cancer vaccines), and local treatments like IRE, SBRT, and HIFU." (PMID 40282495, 2025).
cancer (continued). "Ongoing research continues to drive advancements in KRAS inhibition, with multiple Phase III clinical trials evaluating both monotherapies and combination approaches in advanced cancers." (PMID 41170373, 2025). "Research indicates that ROS can influence tumorigenesis and cellular transformation by oxidizing cysteine residues, which subsequently activate the three most prevalent oncogenic switch genes in human cancers: HRAS, NRAS, and KRAS." (PMID 40181979, 2025). "In mesenchymal-like cell lines, we identified a clear synergistic effect when combining KRAS G12C inhibitors and pemigatinib suggesting that FGFR activation is a key survival pathway for mesenchymal-like cancer cells treated with KRAS G12C inhibitors." (PMID 40788860, 2025). "This transduction process produced the viral oncogenes HRAS and KRAS, which were later shown, along with NRAS, to play key roles in human cancer." (PMID 40906088, 2025). "Notable exceptions were NF1, KRAS, and BRAF alterations in basal-type cancer, as well as increased NF1 and KRAS in HER2-positive disease." (PMID 40080721, 2025). "Researchers have also tried to knock down amplified MET in these cells using siRNA, and cancer cells retained their sensitivity to sotorasib, indicating the importance of MET amplification as an off-target resistance to KRAS inhibitors." (PMID 40597785, 2025). "Early evidence of the involvement of DUSP4 in cancer was provided by Yip and colleagues, who showed that PDAC cells expressing oncogenic KRAS upregulates the expression of DUSP4 to counteract ERK1/2 pathway activation." (PMID 40943262, 2025). "Considering the high prevalence of KRAS point mutations in human tumors and the responsive role of REGγ in KRAS oncogenic signaling, inhibitors targeting the REGγ-proteasome complex could enhance antitumor activity and represent a broadly applicable approach in cancer therapy." (PMID 40091835, 2025). "As G12C is the most common KRAS oncogenic variant in LUAD, we used a recently developed KRASG12C-driven LUAD mouse model (named KcP) to test whether the additional loss of SETD2 (named KcP;Setd2) impacted cancer pathogenesis in vivo like it does in a G12D oncogenic mutant background." (PMID 40462961, 2025). "In the context of KRAS inhibition therapies, EMT emerges as a prominent mechanism driving acquired drug resistance, ultimately contributing to the failure of cancer treatment." (PMID 39950162, 2025). "This inverted chimeric design establishes proof of concept for ligand-directed, dual silencing of KRAS and MYC in cancer and constitutes an innovative molecular strategy for cotargeting any two genes of interest, which has broad implications." (PMID 40762837, 2025). "In NSCLC, TBK1 is a key factor in the KRAS-induced oncogenic transformation of mouse embryonic fibroblasts; the activation of TBK1 by upstream signaling inhibits the apoptosis of cancer cells." (PMID 40076567, 2025). "As a result of their studies, they established that combination of inhibitors of KRAS G12C, PI3K and SHP2 demonstrated anti-cancer activity in mouse models of acquired resistance to sotorasib (AMG510)." (PMID 40597785, 2025). "In contrast to KRAS and NRAS, HRAS undergoes exclusively farnesylation through FTase, making FTIs potentially helpful in treating HRAS-mutant cancers." (PMID 40335986, 2025). "These pan-KRAS inhibitors target KRAS in the inactive “OFF” state, while sparing HRAS and NRAS, and exert antitumor activity in preclinical cancer models." (PMID 39711431, 2025). "Targeting RAS or its downstream effectors, such as the MAPK signaling pathway, has been a longstanding goal in cancer research, and recent progress has been made with the development of MAPK and KRAS G12C small-molecule inhibitors." (PMID 40563570, 2025).